MYC (MYC proto-oncogene, bHLH transcription factor)
Diseases named in the same sentence as MYC in open-access papers (continued):
Sharing a sentence is not in itself a finding about the gene and the disease.
cancer (continued). "The knockdown of SULT2B1b in vitro suppresses tumor cell growth and promotes apoptosis and cell cycle arrest in Hepa1-6 cells by increasing the pro-apoptotic factor (FAS) expression, and downregulating the anti-apoptotic factor BCL-2, cyclinB1, and MYC, promoting cancer cell death." (PMID 39280099, 2024). "Of the known hallmarks of cancer, MYC dysregulation has been reported to result in angiogenesis, cell replicative immortality, cell invasion and migration, alterations in cellular energetics, insensitivity to growth signals, and evading immune recognition and programmed cell death." (PMID 38390324, 2024). "Thus, our data suggest that high MYC expression drives resistance to CDK4/6i by reducing pRB1 protein abundance in cancer cells." (PMID 38424044, 2024). "In this study, we found that the chromosome 17q locus, which is frequently gained in MYC-driven cancers, houses numerous genes essential to cancer cell survival that are implicated in pre-mRNA splicing, ribosome and mitochondrial biogenesis, and other biological functions." (PMID 38488852, 2024). "Popular target cancer-relevant genes include MYC, KRAS, c-KIT, BCL-2, and hTERT." (PMID 39125057, 2024). "The inhibition of MYC for cancer therapy is a very active area of preclinical research." (PMID 39830506, 2024). "Conversely, MYB could also activate miR-200, whereas ZEB1 could directly suppress MYB expression in breast cancer cells, which suggests a context-dependent role of MYC in certain cancers." (PMID 38835346, 2024). "Aberrant upregulation of the MYC signaling pathway is frequently observed in many types of cancers." (PMID 39264149, 2024). "MYC can therefore be considered a priority target for cancer therapy." (PMID 37935464, 2024). "Additionally, the concept of “cysteine addiction” in cancer is linked to the MYCN gene; cysteine depletion triggers extensive lipid peroxidation, suggesting its pivotal role in MYC-driven cancer processes." (PMID 39981299, 2024). "It has been suggested that MYC may function as a dominant downstream effector that mediates the antitumor effects of FGFR inhibition in FGFR addicted cancer cells." (PMID 39031286, 2024). "Moreover, the recurrent HPV integration analysis at the TAD level revealed both the direct and long‐range effect of HPV integration on the expression of cancer‐related genes (such as MYC, PVT1, TP63 and ERBB2)." (PMID 38013620, 2024). "Notably, ODC transcription is directly controlled by MYC; therefore, upregulation or amplification of MYC leads to increased polyamine biosynthesis in malignant tumors." (PMID 38761252, 2024). "Thus, our results provide intriguing cellular evidence pointing to MYC as an attractive target for preventing or overcoming CDK4/6i resistance in cancer cells." (PMID 38424044, 2024). "Indeed, MYC is one of the first oncogene identified in human cancer, described as a cellular homolog of the avian retroviral oncogene v-myc." (PMID 39482742, 2024). "Notably, glutamine is essential for the survival of cancer cells with oncogenic MYC, K-Ras, and PIK3CA, and these cells use glutamine extensively for anabolic processes." (PMID 39051546, 2024). "We identified BMI1, MYC, NANOG, and OCT3/4 (POU5F1 gene) pluripotency markers as the most prominent transcription factors associated with HDAC2 gene expression, highly supporting HDAC2’s association with cancer stemness." (PMID 39063083, 2024). "Here, the authors show that MYC-associated cancer has a dependency on tryptophan not because of translation regulation, but Indole 3-Pyruvate synthesis." (PMID 38769298, 2024). "Additionally, c-MYC inhibits differentiation in normal hematopoietic, mesenchymal, adipocytic, neuronal, and muscle cells, as well as in cancer cells such as pheochromocytoma and erythroleukemia." (PMID 38547242, 2024).
cancer (continued). "Digitoxin, a drug targeting this circuit, might be a promising therapeutic agent for precisely targeting cancer cells affected by MYC." (PMID 39018261, 2024). "Notably, the MYC target v1 pathway is reported to be an important oncogenic pathway in cancer development." (PMID 37615858, 2024). "MYC can mediate the transcription of rRNA to promote ribosome biosynthesis, improve the efficiency of cell protein synthesis or change protein expression profiles to meet material demands for the rapid proliferation of cancer cells." (PMID 38594783, 2024). "Different mechanisms drive abnormal MYC activation in human cancers." (PMID 39594704, 2024). "Furthermore, signalling pathways such as the MYC pathway, which are commonly dysregulated in cancer, play crucial roles in promoting the Warburg effect." (PMID 37740039, 2023). "Nevertheless, we note that MYC is frequently activated in cancers driven by other oncogenes." (PMID 36897988, 2023). "We also found that HNRNPK might co-regulate downstream target genes with MYC, and play important roles in cancer." (PMID 36681772, 2023). "MYC is one of the most highly amplified proto-oncogenes in many types of human cancers." (PMID 36632215, 2023). "MYC, as a carcinogenic gene, is usually activated or up-regulated in cancer." (PMID 36969848, 2023). "MS67 is more effective than WDR5 inhibitors in effectively and selectively depleting WDR5, inhibiting transcription of WDR5 regulatory genes, reducing MLL complex components and chromatin binding parts of c-MYC, and inhibiting the proliferation of cancer cells." (PMID 36770884, 2023). "Therefore, several efforts have been put forward to identify molecules that dampen MYC activity in cancer." (PMID 37175848, 2023). "Some lines of evidence have shown that ACC1/2, CPT1A, and MYC alterations might be critical to lipid metabolism remodeling in cancer." (PMID 37525297, 2023). "Aberrant MYC is well known to set off genomic instability followed by cancer initiation." (PMID 36776299, 2023). "These genes include well annotated tumor-suppressor genes and oncogenes (e.g., TGFBR2 and MYC as well as genes that have never been previously linked to cancer in general, or to increased BC risk (including ADCY3, ATXN7, CFL1 and LPAR2)." (PMID 36991492, 2023). "It is also differentially regulated in MYC-driven cancers, among others in BL." (PMID 37766215, 2023). "The most frequently amplified genes in all cancers are MYC, EGFR and ERBB2 (HER2)." (PMID 37298484, 2023). "SP1 is a METTL3 target that regulates c-MYC expression and plays oncogenic roles in cancer." (PMID 39872957, 2023). "The presence of MYC-expressing fibroblasts in the local metastatic environment assists in promoting colonization by creating a microenvironment conducive to lymphangiogenesis, thereby supporting the survival of cancer cells." (PMID 37755397, 2023). "Thus, our CRISPR/Cas9 screen revealed known and novel MYC‐dependent vulnerabilities in the studied cancer cells." (PMID 37519063, 2023). "The oncogene c-MYC is abnormally highly expressed in ~70% of human cancers." (PMID 36894688, 2023). "Upregulation of MYC expression frequently occurs in cancers." (PMID 37496997, 2023). "Of the three n‐MYC‐positive patients, all patients recurred and one died of cancer." (PMID 36694106, 2023). "The c-MYC gene exhibits overexpression in a staggering 70% of human cancers, including TNBC." (PMID 38275631, 2023). "Moreover, the compound can inhibit c-MYC transcription and cancer cell proliferation (IC50 of 4.7 μM) in Burkitt’s lymphoma (RAJI) cell line." (PMID 36979947, 2023). "MYC is a well-known transcription factor involved in various types of cancers." (PMID 37105715, 2023).
cancer (continued). "MYC signaling participates in a broad spectrum of intracellular biological processes of cancer cells, including proliferation, migration, invasion, differentiation, apoptosis, DNA damage response, and metabolism, which contributes to the development of different kinds of cancer." (PMID 37596667, 2023). "These GO terms were also correlated with MYC expression in a variety of cancer cell lines." (PMID 36830948, 2023). "Analyses of RNA-seq datasets across multiple cancers showed a negative correlation of HNRNPH gene expression with MYC hallmark enrichment, consistent with the effect of hnRNP H on HRAS splicing." (PMID 37399401, 2023). "Furthermore, the HRD group defined by our genomic signatures displays the characteristic features expected of such cancers, including MYC amplification and elevated POLQ expression." (PMID 37919776, 2023). "Thus, the MYC signaling pathway is deemed as being among the principal culprits responsible for the dysregulation of polyamine metabolism in cancer." (PMID 38049863, 2023). "Targeting these mechanisms could destabilize MYC and offer therapeutic benefits for MYC-driven cancers." (PMID 37755397, 2023). "However, MYC-driven cancer cells survive the accumulation of DNA-damage and maintain DNA replication." (PMID 37755397, 2023). "MYC is an oncogene and is well known to play important roles in cancer progression and metastasis." (PMID 37444499, 2023). "There is therefore an unmet need in developing cancer therapies against MYC." (PMID 36684069, 2023). "In addition, later studies revealed that ribosome-free RPs can also regulate cancer cell growth, migration, and autophagy through c-MYC, JAK/STAT3, and mTOR signaling pathways in response to nucleolar stress." (PMID 37087976, 2023). "Interestingly, amplification of PKHD1L1 and other genes at a similar distance from MYC but in the opposite direction from TONSL was observed in only 60% of MYC-amplified cancers." (PMID 37298484, 2023). "Thus, it is proposed by the MYC-studying community that instead of targeting individual functions of MYC in different hallmarks, it is much more effective to “chop the MYC tree” to halt cancer cells from progressing." (PMID 37601651, 2023). "Together, these data suggest that SP1, HIF1A, and MYC have crucial roles in cancer development, and that interfering with their activity could negatively impact cancer development and progressions." (PMID 37998757, 2023). "Because of this, MYC is an attractive therapeutic target for cancer therapy." (PMID 37130865, 2023). "Beyond their role in immunity, all of these factors contribute to keeping the level of NF-kB activation high, and persistent inducing and amplifying side effects of NF-kB such as cyclin D1 and c-MYC transcription, which in turn, play important roles in cancer progression." (PMID 37108333, 2023). "Our study pointed out for the first time that MYC-targeting compounds could potentially increase the O-GlcNAcylation level in cancer cells and compromise the antitumor effect of MYC inhibition." (PMID 36632215, 2023). "Recently, MYC has gained increasing attention as a key regulator involved in cancer metabolism." (PMID 36803784, 2023). "In the stage of reactivation, some QCCs may decrease SOX1 and re-express MYC protein, resulting in increased abundance of proliferative cancer cells." (PMID 37369660, 2023). "This dual inhibition enhances MYC protein degradation leading to the inhibition of cancer cell growth and metastasis, which renders this approach promising for the development of advanced cancer therapeutics." (PMID 36969025, 2023). "Therefore, another potentially valid approach against MYC-driven cancers is to target the kinases that support the Myc oncogenic functions." (PMID 36902175, 2023).
cancer (continued). "Overall, these results suggested that, across multiple cancer models, MYC disrupts circadian transcriptional oscillation and instead promotes static (non-oscillatory) regulation of processes such as biosynthesis, metabolism, and extracellular matrix-related gene expression programs." (PMID 37639465, 2023). "Therefore, a particular G-quadruplex structure is bound by a crescent-shaped thiazole peptide that enters the nucleus and preferentially stabilizes MYC quadruplexes over other promoter G-quadruplexes leading to MYC transcription inhibition in cancer cells." (PMID 36969025, 2023). "The MYC, a proto-oncogene is frequently activated in human cancers through a variety of mechanisms." (PMID 37053209, 2023). "Moreover, our findings indicate a significant association between these genes and certain TFs, such as MYC and FOS, which are known to be involved in the processes of proliferation, metastasis and apoptosis in many cancer types." (PMID 37861558, 2023). "MYC has been shown to play pivotal roles in cancer initiation and its maintenance." (PMID 37400551, 2023). "Moreover, other USPs that regulate c-MYC turnover in different cancers also tend to directly interact with c-MYC." (PMID 36985413, 2023). "Performance of the screen in MYC‐dependent cancer cell lines conducted in duplicate." (PMID 37519063, 2023). "MYC-amplified cancer cells are characterized by inadequate reduction/oxidation balance with accumulation of reactive oxygen species, accelerated entry in S phase and impairment in the expression of genes implicated in purine and pyrimidine biosynthesis and in the regulation of the HR pathway." (PMID 37842243, 2023). "Interestingly, the region around MYC that was amplified differed among different cancer types, suggesting tissue or lineage specific dysregulation." (PMID 37415185, 2023). "The connection between MYC, lncRNAs and cancer has been analyzed in several reviews." (PMID 36849510, 2023). "Increased chromatin accessibility at MYC locus is observed across different cancer types." (PMID 36866275, 2023). "Targeting MYC transcriptional regulation is a promising strategy for cancer treatment." (PMID 37755397, 2023). "To assess whether MYC functioned as a cell-intrinsic mediator of mTORi resistance, we leveraged pharmacogenomic datasets derived from a compendium of human cancer cell lines." (PMID 37642941, 2023). "In addition, in vitro experiments also found that miR-32 transfected cells have lower expression of FBXW7 and higher expression of cancer-related proteins c-Jun and c-MYC." (PMID 36998461, 2023). "Hence, MYC plays a pivotal role in various processes in cancers, including tumorigenesis, metabolism, metastasis, and immune modulation 7-9." (PMID 36632215, 2023). "Mitotic spindle and MYC targets were regulated by more RBPs across all four cancers." (PMID 36681772, 2023). "Since then, MYC has emerged as one of the most important drivers of human cancers." (PMID 37755396, 2023). "In addition, in several studies, these inhibitors exhibited significant therapeutic effects in MYC-driven cancers (including neuroblastoma, small-cell lung cancer, and multiple hematopoietic cancers)." (PMID 36966168, 2023). "Since stabilization of c-MYC by different USPs in different cancers is underpinned by direct physical interaction between both molecules including USP37, it is, therefore, also conceivable that in the ABC subtype of DLBCL, c-MYC is likely regulated by direct interaction with USP37." (PMID 36985413, 2023). "This stresses the need to identify the Achilles’ heel(s) of MYC-driven cancers." (PMID 37642941, 2023). "In conclusion, we have demonstrated that USP45 may play a critical role in enhancing cell survival after cancer treatments, and USP45 inhibition causing MYC destabilization may provide a new strategy for clinical CSC treatments." (PMID 36765885, 2023).
cancer (continued). "Therefore, there is an ongoing quest for novel effective MYC inhibitors for an improvement of cancer therapy with targeted drugs." (PMID 37570631, 2023). "Since the metabolic recycling behavior was only observed in oncogenic cells (specifically, MYC-ON cells in this study), a therapeutic approach interrupting this process could target cancer cells only and spare normal cells." (PMID 36417583, 2023). "Therefore, novel and potentially impactful findings—such as the discovery of an important c-MYC cofactor like WDR5—must be investigated in the context of cancers that are maintained by N-MYC to fully understand any broad-reaching significance." (PMID 37336886, 2023). "Thus, c-MYC can play a significant role in the regulation of proliferation in PKA-dependent cancers." (PMID 36692000, 2023). "Furthermore, mTORC1 not only regulates GDH, but also promotes glutamine uptake by cancer cells by positively regulating GLS through S6K1-dependent c-MYC regulation." (PMID 36959802, 2023). "Targeting MYC mRNA translation provides an alternative approach to combating MYC-driven cancers." (PMID 37755397, 2023). "In cancer, but also in normal cells, excessive c-MYC potently promotes proliferation, facilitates evasion of metabolic checkpoints, accelerates the S-phase entry and duration, and causes replication stress especially when the resources do not meet the requirements." (PMID 37095097, 2023). "Targeting MYC stability offers a potential approach for suppressing MYC-dependent cancers." (PMID 37755397, 2023). "Deregulation of the MYC proto-oncogene contributes to many cancers." (PMID 37399401, 2023). "Due to the importance of MYC as a regulator of both cancer and the TME, MYC inhibitors may be a holy grail of anticancer drugs." (PMID 37998757, 2023). "This shows the importance of MYC overexpression in the regulation of cancer development and suggests that super-enhancers might be a potential target for anticancer therapy." (PMID 37998757, 2023). "Conversely, MSI2 is a crucial regulator of cancer stem cell programs by acting on the stability and translation of target mRNAs that encode key proteins of oncogenic signaling pathways (e.g., TGFβR1/SMAD3, NUMB/Notch, PTEN/mTOR, MET, and MYC)." (PMID 37107676, 2023). "Of them, 57 RBPs were found essential for the growth of cancer cells with highly upregulated MYC." (PMID 37469704, 2023). "However, the same IACS-010759 treatment did not affect basal levels of MYC in normal human brain astrocytes or NSCs, highlighting that complex-I inhibition selectively suppresses MYC in cancer cells." (PMID 37130865, 2023). "Taken together, the MYC regulation reflects cancer-specific functions of the core clock components." (PMID 36937362, 2023). "Importantly, the transgenic expression of Omomyc in vivo was employed to model for the first time systemic MYC inhibition, demonstrating a dramatic therapeutic impact and the viable therapeutic window of inhibiting MYC in cancer." (PMID 36765784, 2023). "In cancer, telomerase reactivation often exists in parallel with MYC overexpression." (PMID 37345011, 2023). "Compared with nonmalignant epithelium, malignant epithelium was enriched in signaling pathways such as oxidative phosphorylation and late estrogen response, with other activated cancer‐related pathways such as MYC target, E2F targets, DNA repair, and G2M checkpoint." (PMID 37017469, 2023).